FUT3 (fucosyltransferase 3 (Lewis blood group))
Diseases named in the same sentence as FUT3 in open-access papers (continued):
Sharing a sentence is not in itself a finding about the gene and the disease.
endometriosis (1 paper, 2019). The growth of functional endometrial tissue in anatomic sites outside the uterine body. "To further understand the increased SSEA-1 immunostaining in endometriosis tissues, we assessed several fucosyl transferase enzymes (FUT3, FUT4) to determine if these differed." (PMID 30496412, 2019). "The transcript for FUT3 and FUT4 used as a surrogate for SSEA1 epitope did not change in the endometrial tissue derived from women with endometriosis (n = 6) compared with the healthy fertile control samples (n = 3)." (PMID 30496412, 2019).
esophageal adenocarcinoma (1 paper, 2025). A malignant tumor with glandular differentiation arising predominantly from Barrett mucosa in the lower third of the esophagus. "TCGA LAT1–FUT3 analysis: CA19-9–producing tumors show lower LAT1 and higher FUT3; an inverse LAT1–FUT3 correlation is specific to PDAC and esophageal adenocarcinoma, implying limited BPA suitability in CA19-9-producing tumors." (PMID 41361823, 2025).
gastroenteritis (1 paper, 2023). An inflammatory disorder that affects the upper and lower gastrointestinal tract. "Human rotaviruses attach to histo-blood group antigens glycans and null alleles of the ABO, FUT2 and FUT3 genes seem to confer diminished risk of gastroenteritis." (PMID 36970669, 2023).
glioblastoma (1 paper, 2020). The most malignant astrocytic tumor (WHO grade IV). "In the same line, a microarray analysis of glyco-gene expression in human glioblastomas carried out by Kroes and colleagues showed the overexpression of the gene FUT3 within a panel of 11 glycosyltransferases overexpressed in human glioblastoma samples in comparison to normal brain tissue." (PMID 33447350, 2020).
glioma (1 paper, 2020). A benign or malignant brain and spinal cord tumor that arises from glial cells (astrocytes, oligodendrocytes, ependymal cells). "In addition, TSA treatment of this low-grade glioma cell line accounted for a significant increase in the transcription rate of MGAT5 and FUT3/7/9." (PMID 33447350, 2020).
infertile (1 paper, 2021). "The results of ROC curve analysis showed that the determination of seminal plasma parameters: CLU, FUT3, and FUT4 concentrations may be helpful in the differentiation of infertile groups of patients with both normal and abnormal seminal parameters." (PMID 34341430, 2021).
leukemia (1 paper, 2023). A malignant (clonal) hematologic disorder, involving hematopoietic stem cells and characterized by the presence of primitive or atypical myeloid or lymphoid cells in the bone marrow and the blood. "The two leukemia cell lines from the sLeX-positive subset where the only ones with convincing FUT7 expression but lacked FUT3." (PMID 37486674, 2023).
meningioma (1 paper, 2024). A generally slow growing tumor attached to the dura mater. "We found that the respective expression of FUT2, FUT3, FUT6, and FUT7 was also increased in the malignant meningiomas—HKBMM and IOMM-Lee." (PMID 38274327, 2024). "FUT1, FUT2, FUT3, FUT6, FUT7, and FUT8 were highly increased in malignant meningioma cell lines." (PMID 38274327, 2024). "High expression of FUT1, FUT2, FUT3, FUT6, FUT7, and FUT8 in malignant meningioma cell lines—HKBMM and IOMM-Lee—may represent a fucosylation signature of mucin-type O-linked glycosylation in malignant meningiomas." (PMID 38274327, 2024).
multiple sclerosis (1 paper, 2025). A progressive autoimmune disorder affecting the central nervous system resulting in demyelination. "The aim of the study is to evaluate SCFA secretion in patients with multiple sclerosis from the West Pomeranian region depending on the genotypes of rs778986 and rs3894326 polymorphisms of the FUT3 gene." (PMID 41515180, 2025).
oral carcinoma (1 paper, 2021). "Further, down regulation of FUT3 with disease advancement suggests its role as a good prognosticator for oral carcinoma." (PMID 34703796, 2021). "In this study, we examined the mRNA expressions of fucosidase (FUCA1) and FUTs (FUTs (FUT3, FUT4, FUT5, FUT6, FUT8) in human oral cancer tissues." (PMID 34703796, 2021). "Therefore, the present investigation was aimed to evaluate the clinical significance of mRNA expressions of various fucosyltransferses (FUT3, FUT4, FUT5, FUT6, FUT8) and fucosidases (FUCA1) in oral cancer progression." (PMID 34703796, 2021).
ovarian tumor (1 paper, 2023). "We observed 24 ABH antigen synthesis‐related genes in which five genes (FUT1, FUT2, FUT3, B3GNT3, and B3GNT2) were up‐regulated and three genes (ST3GAL3, ST3GAL4, and B3GALT2) were down‐regulated in ovarian tumor tissue versus adjacent tissues in all samples." (PMID 36415180, 2023).
prostate carcinoma (1 paper, 2024). A carcinoma that arises from epithelial cells of the prostate gland. "Overexpression of the Fut3 gene has been implicated in the development of prostate cancer." (PMID 38911244, 2024).
tongue cancer (1 paper, 2021). A malignant neoplasm affecting the tongue. "There was a significant up regulation of FUT3, FUT4, FUT5, and FUT8 (P = 0.019, 0.025, 0.087, and 0.034, respectively) in patients with tongue carcinoma in comparison with patients with buccal carcinoma as a primary site." (PMID 34703796, 2021).
cancer (29 papers, 2011 to 2025). A tumor composed of atypical neoplastic, often pleomorphic cells that invade other tissues. "In particular, variations in both FUT2 and FUT3 have been associated with various types of disease including different types of cancer and intestinal diseases." (PMID 40244459, 2025). "The study findings revealed a noteworthy positive association between the expression level of FUT3 and the invasive potential of cancer stem-like cells." (PMID 38911244, 2024). "This was unexpected, considering that several members of this group (FUT3-7) are responsible for the biosynthesis of well-known cancer-associated Lewis type antigens and their sialylated counterparts sialyl Lewis x and sialyl Lewis a." (PMID 35565254, 2022). "Moreover, fucosylation is more common in cancer stem cells compared to parental tumor cells, and overexpression of FUT3 is typically associated with cancer progression and poor prognosis." (PMID 38911244, 2024). "FUT3 (fucosyltransferase 3), which plays a role in the fucosylation of glycosphingolipids, was significantly downregulated in MSCs compared to cancer cell lines." (PMID 39621192, 2025). "CCLE data showed that CA19-9-high cancer cell lines had significantly upregulated FUT3 (q = 0.003), B3GALT5 (q = 0.003), and FCSK (q = 0.003) mRNA levels compared with CA19-9-normal cell lines." (PMID 41361823, 2025). "Our results initially indicated that the addition of 2F-PerAcFuc, an inhibitor of fucosylation, resulted in the down-regulation of the Fut3/CD15s pathway in both cancer stem-like cells and the xenograft model." (PMID 38911244, 2024). "Coexpression data from the Cancer Cell Line Encyclopedia supported this association partly and showed CDX1 positively correlated with FUT3 (Pearson's correlation 0.63)." (PMID 26537799, 2016). "Bioinformatics analysis of CA19-9-high cancers revealed elevated FUT3 expression." (PMID 41361823, 2025). "The results indicated that FUT3 was significantly upregulated in cancer tissues and involved in the NF-κB signaling pathway, suggesting that FUT3 dysregulation might play a key role in LUAD pathogenesis and progression." (PMID 37946130, 2023). "Interestingly, FUT3 was highly expressed from early-stage cancer, whereas FUT4 gradually increased with tumor progression." (PMID 37168374, 2023). "We employed Sangerbox database to investigate the expression of FUT3 in pan-cancer." (PMID 37946130, 2023). "Evidence exists for increased FUT3 activity and the resultant increased abundance of Lewis antigen-bearing glycolipids during hepatic inflammation, neural differentiation, and in epithelial cancer cells." (PMID 21527995, 2011). "Based on our data, it is evident that inhibition of FUT3 and FUT8 plays a significant role in the production and stability of CD15s and E-cadherin, which are important cancer cell markers." (PMID 38911244, 2024). "We found that FUT2, FUT3, and FUT8 exhibited significantly elevated expression levels in older patients with both cancers when compared with young patients." (PMID 38456503, 2024). "The overexpression of FUT3 and FUT5, evidenced in cancer cells, correlates with the increased presence of Lewis antigens on cancer cell surface that facilitates carcinoma cell–endothelial cell interactions, tumor cell rolling and metastasis." (PMID 34070747, 2021). "The results of the study demonstrated a significant reduction in the expression levels of fucosyltransferase 3 (FUT3) and fucosyltransferase 8 (FUT8) in both cancer stem-like cells and tumor tissues upon treatment with 2F-PerAcFuc, in comparison to the control groups." (PMID 38911244, 2024). "Recently, FUT3 knockdown was shown to disrupt binding of circulating cancer cells to endothelial cells without affecting hematopoietic cell adhesion." (PMID 26509633, 2015). "Therefore, it appears that FUT3 (in solid malignancies) and FUT7 (in leukemic cells) represent rate-limiting enzymes of sLeA/X synthesis and could be useful targets to block sLeA/X synthesis in cancer cells." (PMID 37486674, 2023).
tumor (26 papers, 2012 to 2025). "Loss of FUT3 across several tumor cell lines/types has been reported to decrease migration, invasion, TGFβ signaling, interaction with E-selectin, metastatic potential in vivo, and drug resistance." (PMID 31450600, 2019). "Focusing on glycosyltransferases expression in tumor tissues, we observed two distinct expression clusters, segregating FUT3, FUT4, FUT6, and ST3GAL4 transcripts, from FUT7, FUT9, ST3GAL3, and ST3GAL6." (PMID 39508360, 2025). "Previous studies have shown high expression of fut3 and fut8 in tumor-sphere and ESCC tumor tissues compared to matched healthy controls." (PMID 38911244, 2024). "We demonstrated that inhibition of fut3 and fut8 using 2F-PerAcFuc directly reduced the production of CD15s and core fucosylation of E-cadherin in the xenograft model of tumor tissue in nude mice." (PMID 38911244, 2024). "Further investigations are warranted to elucidate the underlying mechanisms through which 2F-PerAcFuc influences FUT3 and FUT8 expression and to assess its broader impact on cellular functions and tumor progression." (PMID 38911244, 2024). "Knockdown of FUT3 significantly inhibited tumor proliferation, migration and glucometabolic alteration in LUAD cells." (PMID 37946130, 2023). "We validated the FUT3 potential tumorigenicity on LUAD in vivo using a mouse subcutaneous tumor model." (PMID 37946130, 2023). "The result demonstrated that downregulation of FUT3 reduced LDH activity while Asatone restored the change in the resected tumor when compared with the control groups." (PMID 37946130, 2023). "For this, we evaluated the general expression of fucosylation-related genes detected in tumour cells using gene sets associated with the GDP-Fuc synthesis (GMDS, TSTA3), fucosyltransferases (FUT2, FUT3, FUT4, FUT6) or both." (PMID 35017635, 2022). "Our data demonstrated that tumor tissues contained significantly lower mRNA levels of FUT3 (2.3 fold), FUT4 (2.7 fold), FUT5 (5.9 fold), FUT6 (3.0 fold), FUT8 (2.0 fold), and FUCA1 (2.6 fold) as compared to adjacent normal tissues." (PMID 34703796, 2021). "B3GNT3 had higher (p > 0.05) and FUT3 had equivalent (p > 0.05) expression in the ductal compartments of tumour tissues as compared to the control tissues." (PMID 32203219, 2020). "In contrast, the ectopic overexpression of FUT3 amplifies sLex levels and promotes cellular adhesion, tumor growth, and metastasis." (PMID 31450600, 2019). "Many studies from other research groups had similar results to our study, in other words, FUT-3 can promote the malignant behavior of the tumor and lead to a poor prognosis." (PMID 28977844, 2017). "TMA technique only displays small representative part of the tumor, and expression of FUT3 is subjectively evaluated." (PMID 28977844, 2017). "The FUT3 in blood or tumor tissue would be new biomarkers for ccRCC detection or prognosis prediction soon." (PMID 28977844, 2017). "In conclusion, DDX39B acts as a tumor promoter in CRC by upregulating the expression of FUT3 and then promoting the fucosylation of TGFβR-I, which subsequently enhances activation of the TGFβ/SMAD2 signaling pathway to facilitate the invasion and metastasis of CRC." (PMID 33436563, 2021). "FUT3 has generally been reported as a crucial mediator of tumor-promoting signaling." (PMID 31450600, 2019). "Furthermore, SCID mice co-injected with tumor cells and EC-Bcl-2 showed significantly higher lung metastasis, that was markedly reversed by the knockdown of E-selectin in EC-Bcl-2 and FAK or FUT3 knockdown in tumor cells." (PMID 26509633, 2015). "FUT3 promotes invasion and immune escape by inducing EMT and enhancing tumor–macrophage communication." (PMID 40852041, 2025). "Analytical results revealed TYMP and HS3ST2 in tumor samples were significantly upregulated and GCNT4 and FUT3 were significantly downregulated." (PMID 41155476, 2025).
tumor (continued). "Our data showed that FUT3 was upregulated from the early stage, while FUT4 progressively increased with the tumor stage, suggesting a linkage conversion of α-fucosylation as the tumor progresses." (PMID 37168374, 2023). "In tumor tissues, the expression of ST3GAL6 was found to be notably reduced, whereas the expression levels of B3GALT2, ABO FUT3, B3GNT3, and B3GNT5 were observed to be significantly elevated." (PMID 37781041, 2023). "Some of the glycoTs genes such as GCNT3, GALNT5, FUT3, B3GNT6 and B3GNT3 were more than 19-fold overexpressed in tumour samples." (PMID 32203219, 2020). "To evaluate the level of FUT3 expressed in ccRCC tumor tissues, we conducted the IHC staining to the TMA of 406 patients and analyzed the FUT3 expression of the ccRCC patients." (PMID 28977844, 2017). "Specifically, in the fucosyltransferase family, overexpression of FUT3 can serve as a molecular marker for poor prognosis, while the high differential expression of FUT11 indicates tumor progression potential, rendering both promising candidates for risk stratification models." (PMID 40852041, 2025). "Compared with young patients with a tumor, we found that the epithelial subset cE03 showed elevated FUT2 and FUT3 and coexpression with tumor-promoting TGFB1 and interleukin 6 cytokine family signal transducer (IL6ST) gene expression in older patients with a tumor." (PMID 38456503, 2024). "Additionally, older patients with a tumor exhibited elevated FUT2, FUT3, and FUT8 coexpression with tumor-promoting IL6ST, IL22RA1, TGFB1, and TGFBR1 genes compared with young tumor." (PMID 38456503, 2024). "Furthermore, the expression levels of macrophages were found to be positively correlated to those of FUT3, a key gene involved in CA19-9 synthesis, indicating a significant correlation with the tumor microenvironment." (PMID 39868376, 2024). "The previous report suggested that the down-regulation of FUT3 and FUT5 in tumor cells reduced the expression levels of sLex antigens, which could reduce the metastatic potential of the tumor cells process." (PMID 33557187, 2021). "In addition, immunochemistry experimental of subcutaneous tumor models and FUT3 knockout mice models were not conducted, which need to be further identified." (PMID 37946130, 2023).
infection (8 papers, 2009 to 2022). The state of being infected such as from the introduction of a foreign agent such as serum, vaccine, antigenic substance or organism. "These concordant data provide strong evidence that FUT2 (secretor) and FUT3 (Lewis) genetic polymorphisms contribute to susceptibility to major strains of RVs and therefore that HBGAs are involved in the infection process." (PMID 30154494, 2018). "Our obtained results may explore the regulatory mechanism of the pig FUT3 gene that affects resistance to the infection caused by E. coli F18 and involved in its application in molecular breeding against bacterial diarrhea in local piglets of China." (PMID 34680980, 2021). "The underlined study may explore FUT3 as a new candidate target in E. coli F18 infection in Chinese local weaned piglets." (PMID 34680980, 2021). "We used mice as model animals to further evaluate whether FUT3 affected E. coli F18 infection in vivo." (PMID 35696408, 2022). "Due to the variable HBGA polymorphism among populations, we aimed to evaluate the association between HBGA phenotypes (ABH, Lewis and secretor status) and susceptibility to rotavirus and norovirus symptomatic infection, and the polymorphisms of FUT2 and FUT3, of children from southeastern Brazil." (PMID 32992989, 2020). "Therefore, this study aimed to analyze the association between rotavirus and norovirus symptomatic infection and HBGA phenotypes, in addition to FUT2 and FUT3 genes polymorphisms, in children from Southeastern Brazil." (PMID 32992989, 2020). "FUT3, belonging to the fucosyltransferase family, regulates the formation of ABH and Lewis antigens and resistance to pathogen infection." (PMID 34680980, 2021). "In the present study, we were able to reinforce the current knowledge that secretors are more susceptible than non-secretors to infection by both rotavirus and norovirus, and that the combination of FUT3 polymorphisms found may reflect the highly mixed Brazilian population." (PMID 32992989, 2020). "We compared infection and diarrhea from these pathogens between FUT2+/FUT3− and FUT2+/FUT3+ children." (PMID 30768135, 2019). "FUT3 and FUT5 have also been shown to be responsible for the α1-4 linkage of fucose, and we only detected the low expression of FUT5 in GES-1 cells by H. pylori strains YN4-62, HLJ011 and HLJ030 infection at 0.5 h." (PMID 33557187, 2021).
metabolic disease (2 papers, 2013 to 2020). A congenital disorder (due to inherited enzyme abnormality) or acquired (due to failure of a metabolically important organ) disorder resulting from an abnormal metabolic process. "Evidence suggests that the expression patterns of FUT2 (Secretor gene) and FUT3 (Lewis gene) can play a role in the predisposition to metabolic diseases." (PMID 32722157, 2020).
bacterial infection (1 paper, 2021). "FUT3 belongs to the family of fucosyltransferase genes and was found to be associated with the mediators of gastrointestinal disease, rotavirus, and bacterial infection." (PMID 34680980, 2021).
gastrointestinal tumors (1 paper, 2021). "FUT3 was highly expressed in the majority of gastrointestinal tumors (TCGA database online website GEPIA27)." (PMID 33436563, 2021).
FUT3 also shares sentences with these, for which no sentence is quoted: ankylosing spondylitis (2 papers); breast infiltrating ductal carcinoma (2); clear cell renal cell carcinoma (2); coronary heart disease (2); Crohn disease (2); inflammatory bowel disease (2); intestinal diseases (2); non-small cell lung carcinoma (2); viral infection (2); acute diarrhea (1); acute myeloid leukemia (1); asthma (1); atrophic gastritis (1); cardia (1); celiac disease (1); COVID-19 (1); cystic fibrosis (1); Diarrhea (1); esophageal cancer (1); gastric adenocarcinoma (1); gastritis (1); gastrointestinal disease (1); hepatic carcinoma (1); inflammation (1); intestinal infections (1); liver cancer (1); lung disease (1); lymph node metastasis (1); malignant meningiomas (1); Meconium ileus (1).
A further 10 diseases each share a sentence with FUT3 in 1 paper.